CD47 (CD47 molecule)
Diseases named in the same sentence as CD47 in open-access papers (continued):
Sharing a sentence is not in itself a finding about the gene and the disease.
tumor (continued). "From this perspective, recent approaches are being evaluated: epigenetic reprogramming of M2-like TAMs into M1-like TAMs; increasing phagocytic activity by CD47/SIRPα blockade; engineering Chimeric Antigen Receptors for Phagocytosis (CAR-P) to increase tumor cell killing." (PMID 34276698, 2021). "In TME, mtDNA of tumor cells were ingested by DCs and activate cGAS to increase IFN-I production in DC cytoplasm; inhibition of CD47 could suppress mtDNA degradation by phagosomes, which contributes to enhance antitumor adaptive immunity." (PMID 35265630, 2021). "In PanNETs, CD47 was overexpressed; its staining in tumor tissue was not only obviously higher than that in adjacent non-tumor tissue, but also significantly higher than that in islet cells." (PMID 33765961, 2021). "When the drug was administered to the tumor site, it not only blocked CD47 on tumor cells to eliminate the ‘do not eat me’ signal but also targeted SIRP α on macrophages and enhanced the phagocytic activity of macrophages." (PMID 34142930, 2021). "In contrast, another report showed that SLAMF7 coexpression on macrophages and tumor cells is not required for CD47-mediated phagocytosis." (PMID 33597728, 2021). "CD47 is a “do not eat me signal” that allows for macrophage immune evasion by tumor cells of different cancers." (PMID 34068316, 2021). "The combination of anti‐CD47 and anti‐CD24 antibodies could offer robust cancer cell‐killing effects and block the vicious cycle for tumor recurrence from cancer stem cells." (PMID 34363319, 2021). "We also investigated the expression of CD47 and PVR on the tumor cell lines by flow cytometry." (PMID 34068552, 2021). "CD47-SIRPα inhibitors and CD40 monoclonal antibody that regulate TAMs could also limit the migration of neutrophils to tumor or deplete neutrophils (NCT02216409, NCT03717103, NCT02367196, NCT01103635)." (PMID 33343560, 2020). "We showed that ATP6AP2 knockdown or CD47 blockade alone inhibited tumorigenicity of SW620 and DLD1 in mice, and a combination of ATP6AP2 knockdown and CD47 blockade elicited a strong inhibition of tumor growth and development." (PMID 33603751, 2020). "Here, the authors show that injection of tumour cells lacking CD47, or cells coated with an anti-CD47 antibody, into mice mounts a strong immune response, resulting in a reduction in tumour growth." (PMID 31996683, 2020). "Antibody-mediated dual inhibition of CD47 and HER2 confirms the advantage of local irradiation compared to inhibition of either receptor alone, although substantial tumor inhibition was also achieved by radiation combined with antibody blockage of CD47 or HER2." (PMID 32929084, 2020). "Interestingly, CD47 expression levels on NK cells and CD8+ T cells were decreased in the tumor compartment." (PMID 32811852, 2020). "For example, anti-CD47 mAbs block a 'do not eat me' signal upregulated on tumor cells to evade macrophage-mediated phagocytosis but is also present on erythrocytes, platelets and other healthy cells." (PMID 32989604, 2020). "Suppression of either CD47 or ATP6AP2 alone in MDA-MB-231 cells demonstrated anti-cancer effects, and a double knockdown revealed a synergistic effect and dramatically inhibited tumor development and lung metastasis." (PMID 33603751, 2020). "In addition, after treatment with MPV-HOAD and CD47 blockade, CT26 colorectal tumor-bearing mice exhibited reduced tumor recurrence." (PMID 32082311, 2020). "TSP-1, HIF-1, CD47, and VEGF all play important roles in inflammation and tumor." (PMID 32733941, 2020). "By targeting tumor-cell CD47 through a decoy receptor (SiRPαFc), reverting the “do-not-eat-me” signal to bystander macrophages, a significant reduction of tumor load was observed in various hematologic malignancies, i.e., CTCL." (PMID 32034661, 2020). "Conversely, in the absence of CD47 recognition, macrophages will maintain active phagocytosis and subsequently clear pathogens, foreign bodies, and tumor cells." (PMID 32296015, 2020).
tumor (continued). "For example, blockade of CD47 promotes uptake of tumor cells by SIRPα+ cDC2, leading to activation of the cGAS-STING pathway, whereas in other tumor models it is production of 2′3′-cGAMP by tumor cells that is responsible for activation of host STING." (PMID 32508825, 2020). "Later, this same group demonstrated that CD47 blockade could sensitize NSCLC to antiangiogenic therapy and potentiate its antitumor effects by enhancing macrophage infiltration and tumor cell destruction." (PMID 33015199, 2020). "Notably, germ cell-like tumor cells showed stronger staining for PDL1, FASL, TRAIL, and CD47 compared with differentiated somatic tumor cells both in primary tumors and liver metastases." (PMID 32218989, 2020). "When the expression level of CD47 on the cell surface increases, the balance is upset, because CD47 sends out a “do-not-eat-me” signal to inhibit the phagocytosis of the tumor cells, promoting the occurrence, and development of tumors." (PMID 32161718, 2020). "For instance, phagocytosis is impaired resulting from tumor cells hijacking “not-eat me” labeling such as CD47-SIRPα to evade the attack of macrophages." (PMID 33505964, 2020). "In the present study, we analyzed the presence of immunomodulatory molecules: PD-L1, CD47, CD73, Fas, and FasL on mature tumor cells (MTCs) and cancer stem cells (CSCs) in lymph nodes (LNs) aspirates and refer it to the lymphocyte subpopulation in peripheral blood (PB)." (PMID 32244422, 2020). "Future trials may prioritize the combination of anti-CD47 therapy with targeted antibodies against known receptors such as GD2, CD47-specific CAR-T cells, NK cells, or tumor vaccines." (PMID 35582455, 2020). "When CD47 was blocked using an antibody on the EVs, it was found that there was no reduction of tumor burden when compared to the iEVs." (PMID 31963216, 2020). "In this study, we aimed to analyze the expression of the CD47 molecule in both tumor-infiltrating lymphocytes and the nonlymphocyte cell fraction of tumoral and paratumoral tissue samples from EC patients." (PMID 32811852, 2020). "Flow cytometry analysis of protein expression profile of unmodified TMVs showed that TMVs express tumor and immune cell markers such as cancer stem cell markers (CD24 and CD44), co-stimulation (CD80 (B7-1)), immunosuppression (CD47, PD-L1), and innate immune cells (Gr1)." (PMID 32295135, 2020). "Here, we revealed the up-regulation of CD47, the negative checkpoint molecule that binds to SIRPα, as an innate immunosuppressive mechanism that limited the anti-tumor effect of VEGF/VEGFR inhibitors." (PMID 31829270, 2019). "CD47 and IDO1 staining in tumours was ranked from low to high intensities." (PMID 31358801, 2019). "To have a better understanding of the effect of anti-CD47 treatment on the morphology and real-time kinetics of microglia response, we performed intracranial in vivo imaging of NSG-Ccr2RFP/wt-Cx3cr1GFP/wt mice grafted with the tumor cell line T387-EBFP2+-Luc." (PMID 30602457, 2019). "Targeting CD47 could trigger macrophage-mediated elimination of the relapsed NSCLC cells, eliciting synergistic anti-tumor effect." (PMID 31829270, 2019). "To evaluate, whether calreticulin expression increases the phagocytic efficacy of CD47 mAb therapy, we cocultured MNNG/HOS tumor cells with bone marrow‐derived M1 macrophages in presence of doxorubicin, CD47 mAb, and combination treatment." (PMID 31376208, 2019). "Importantly, tumor-infiltrating CD68+ M and tumor expression of CD47 correlated with clinico-pathological features of PDAC patients in our study." (PMID 31771616, 2019). "As expected, treatment of PC9GR and HCC827GR cells with gefitinib for 48 h did not affect the expression levels of CD47 and failed to promote tumor cell phagocytosis by dendritic cells." (PMID 32082304, 2019). "Moreover, in ATC xenotransplanted NSG mice, anti-CD47 mAb treatment increased TAM frequencies and promoted phagocytosis of tumor cells, resulting in significantly delayed tumor growth." (PMID 30938231, 2019).
tumor (continued). "CD47 is a “do not eat me” signal, overexpressed in myeloid malignancies that leads to tumor evasion of phagocytosis by macrophages." (PMID 32038992, 2019). "The high-expression of CD47 and CD274 on cancer surface may be the reason why circulating tumor cells could escape from the immune system." (PMID 30872703, 2019). "Blocking both CD47 and CD274 may be a good method for treatment of tumor metastasis, and at the same time this could be a solution to the limitations of single antibody limitation, fewer checkpoints and poor targeting." (PMID 30872703, 2019). "In contrast to HPV(−) tumor, exosomes released by HPV (+) tumors do exhibit prolong immunogenic interaction with immune cells due to the regulation of the expression and/or activity of CD47 on the membrane of cancerous cells." (PMID 31861233, 2019). "In the anti-CD47 or anti-CD274 treated group, tumor nodules were reduced in the lungs." (PMID 30872703, 2019). "Other studies have shown the dependence of NK cell-associated cytotoxicity on CD47 expression, and we have confirmed that the absence of CD47 leads to higher amounts of active NK cell populations, leading to tumor containment and sustained rejection." (PMID 31882679, 2019). "FACS analysis using anti-mouse immunoglobulin revealed that the therapeutic CD47 mAb had effectively bound on the surface of CD45− EpCAM+ tumor cells (data not shown)." (PMID 30938231, 2019). "Intriguingly, CD47 blockade decreased the tumor burden in the Panc02 but not in the MPC-83 syngeneic mouse model." (PMID 31771616, 2019). "Although VEGF inhibitor increased tumor hypoxia in A549 and NCI-H1975 xenograft models, there are only 4 to 6% of total CA9+ cells that were CD47+, demonstrating that hypoxia was not the major cause of CD47 upregulation during anti-angiogenic therapy." (PMID 31829270, 2019). "The antibodies could effectively block the expressions of CD47 and CD274 on the cell surface and stably attached to tumor cell surface for several hours." (PMID 30872703, 2019). "In contrast, CD68+ M and CD47 expression did not correlate with most of the clinico-pathological variables, such as histological grade, clinical stage, tumor diameter, vascular invasion, and postoperative chemotherapy." (PMID 31771616, 2019). "In this work we determined that the ICD induced by the CD47-agonist peptide, PKHB1, has a therapeutic potential, as the PKHB1-TCL was able to induce antitumor immune responses ex vivo and in vivo in an established L5178Y-R tumor." (PMID 31275386, 2019). "When a previously dormant immune system incapable of recognizing and attacking a growing tumor is presented with syngeneic inactivated tumor cells lacking cell-surface CD47, it will lead to the mobilization of circulating macrophages." (PMID 31882679, 2019). "Surprisingly, there were no obvious tumor nodules in the anti-CD47 or anti-CD274 group compared with other control groups." (PMID 30872703, 2019). "Given the increasing evidence of the involvement of tumor microenvironment in remodeling cancer cell responsiveness to TKI therapy, we investigated the expression of CD47 and ecto-CRT in PC9 and HCC827 cell lines after the acquisition of gefitinib resistance in vitro." (PMID 32082304, 2019). "For the MPC-83 tumor model, anti-PD-L1 mAb but not anti-CD47 mAb treatment showed significant inhibitory effect on the tumor growth." (PMID 31771616, 2019). "The “don't eat me” ligand CD47 is highly overexpressed in HCC samples and preventing interaction with SIRP1α by blocking anti-CD47 antibodies augments macrophage efferocytosis of HCC cells in vitro and diminishes HCC tumor growth in in vivo xenograft models." (PMID 31798592, 2019). "To confirm the hypothesis and realize more effective treatment and inhibition immune evasion of CTCs, we selected mice tumor 4T1 cells as a CTC model, and blocked two immune checkpoints: CD47 and CD274." (PMID 30872703, 2019).
tumor (continued). "Anti-CD47 antibodies or engineered SIRPα–Fc fusion were shown to restore macrophage ability to phagocytose cancer cells and prime cytotoxic CD8 T-cells, leading to the tumor regression in several tumor models and in clinical trials." (PMID 31547627, 2019). "Then, we isolated tumor cells from NSCLC tumors in VEGFR1-Fc-treated mice and investigated whether targeting CD47 could eliminate the relapsing NSCLC cells." (PMID 31829270, 2019). "The ADC targeting CD47 that an immunosuppressive receptor and TAA double positive (CD47+/TAA+) tumor cells could block the immunosuppression to augment the killing activity of the ADC." (PMID 31068807, 2019). "Thus, both CD47 and CD274 proteins contribute to the tumor micro-environment by affecting T cell activation and angiogenesis, and the results confirmed that the percentage of T cells and NK cells were increased with the blockade of CD47 or/and CD274." (PMID 30872703, 2019). "The SIRPα end of the ARC bound immobilized CD47 at 3.59 nM affinity and also CD47 on the surface of human tumor cells both in vitro and in vivo, but importantly, did not bind human platelets, RBCs, nor induce hemolytic activity." (PMID 30400822, 2018). "This group found that SLAMF7 serves as a key receptor promoting the phagocytosis of SLAMF7-expressing hematopoietic tumor cells by macrophages when the inhibitory SIRP-α receptor on macrophages is blocked by antibodies from detecting its ligand, CD47, on the same tumor target cells." (PMID 30455698, 2018). "Another benefit of targeting SIRPα on phagocytes rather than CD47 on tumors is the potential for synergy with tumor‐specific mAbs to increase phagocytosis and enhance the anti‐tumor response." (PMID 30460349, 2018). "In a previous study, we used this technology to conduct an immunotherapy approach based on silencing the SIRPα gene in macrophages and the CD47 gene in breast cancer MCF-7 cells, to avoid their interaction and provoke the elimination of tumor cells by macrophages in co-culture experiments." (PMID 30399174, 2018). "To date, some studies have shown that CD8+ T cells play a critical role in mouse anti-CD47 blockade-induced tumor reduction even though the target is not directly on the T cells." (PMID 30062558, 2018). "Expressed on most tumor cells, including GBM, CD47 signals “don't eat me” to macrophages." (PMID 30854331, 2018). "Signal replacement of CD47 by CD40L may uniquely poise DCs/macrophages in the tumor microenvironment for activation and cross-presentation of tumor antigens following enhanced tumor cell phagocytosis." (PMID 30400822, 2018). "Similar to the results with the cell lines, ex vivo coating of these primary tumor cells and primary CSCs with anti-CD47 antibody, but not controls, resulted in complete inhibition of subcutaneous engraftment." (PMID 28484448, 2017). "We show that the lack of CD47 in tumor stromal cells promotes angiogenesis and enhances vascular integrity and stability, leading to accelerated tumor progression." (PMID 27283989, 2017). "We tried to highlight EGFP-dim cells using anti-CD47 (data not shown), which clearly labelled the tumour cells in the spheroid but failed to clearly detect the disseminated cells." (PMID 28706234, 2017). "Comparison of the CD47 enhancer landscapes of tumour cells versus corresponding normal (non-tumour) cells revealed that SEs were present only in the tumour cells." (PMID 28378740, 2017). "Different modes of immune evasion were seen across 12 tumours with up-regulation or consistent expression of CD47, unlike other immune evasion genes such as PDL1, FUT4, CTLA4 and BTLA which were downregulated in a few samples." (PMID 28886030, 2017). "Differences in tumor volumes evaluated by MRI scan were not evident in rats when treatment with anti-CD47 was initiated at 4 weeks after implantation relative to controls." (PMID 28076333, 2017).
tumor (continued). "To test whether CD47 also regulates vascular integrity in cancer tissues, we analyzed vascular endothelial (VE)-cadherin (CD144) expression in the tumor vasculature by immunofluorescence staining." (PMID 27283989, 2017). "We have previously shown that TTI-621, a soluble SIRPαFc fusion protein that blocks the CD47 “do-not-eat” signal, promotes tumor cell phagocytosis by IFN-γ-primed macrophages." (PMID 29084248, 2017). "Interestingly, activation of the TSP-1 receptor, CD47, induces autophagy in RAS-expressing cancer cells to quell tumor growth." (PMID 28174297, 2017). "To determine if CD47 could be involved in PEDF-stimulated phagocytosis, we measured CD47 expression in PC3 and CL1 tumor cells expressing PEDF or control plasmid." (PMID 28403150, 2017). "It is designed to block the CD47 “do-not-eat” signal and engage macrophage Fcγ receptors to enhance phagocytosis and anti-tumor activity." (PMID 29084248, 2017). "Treatment with anti-CD47 antibody thus did not inhibit tumor growth when injected at 4 weeks after implantation into solid tumors." (PMID 28076333, 2017). "Here we investigated the role of CD47 expression in non-tumor stromal cells in tumorigenesis by comparing tumor angiogenesis and progression in wild-type (WT) and CD47-deficient mice after injection of syngeneic cancer cells." (PMID 27283989, 2017). "Furthermore, after anti-mouse CD47 treatment, significantly more interferon (IFN)-γ spot-forming antigen-specific CD8+ T cells are present in the tumor, and T cell-mediated memory response is formed to protect mice from tumor re-challenge." (PMID 28077173, 2017). "Moreover, PAR2 is involved in the regulation of CD47+ HCC stem cells, contributing to tumour initiation, self-renewal and metastasis." (PMID 27473374, 2016). "This study is the first to reveal that CD47 was overexpressed in NSCLC tumor tissues and cell lines, compared to matching adjacent non-tumor tissues and normal bronchial epithelial cells, respectively." (PMID 27411490, 2016). "Blocking the surface of cells' CD47 with anti-CD47 antibodies has been reported to inhibit tumor growth by blocking the defense “do not eat me” signal of malignant cells, enabling macrophages to engulf the cancer cells." (PMID 26318039, 2015). "The administration of anti-CD47 blocking antibodies enhances phagocytic uptake of tumor cells, but surprisingly not healthy cells." (PMID 25688334, 2015). "This implies that CD44, CD47 and c-met may have synergistic effects on the development of OCCC and probably are biomarkers of tumor stem cells of OCCC." (PMID 25658794, 2015). "It has been reported that CD47 antibodies enhance nonphagocytic tumor cell killing by neutrophils and NK cells." (PMID 26390038, 2015). "Consequently, the second part of the branching process (related to CD47, CD44 and MET) occurs while tumour cells are still in the mammary duct." (PMID 25978366, 2015). "It should be noted that similar inhibition of tumor growth is observed when irradiating TSP-1 null mice, thus suggesting that anticancer targeting of TSP-1:CD47 interaction would be of a greater relevance than disrupting CD47:SIRPα." (PMID 26578962, 2015). "The “do not eat me” signal provided by CD47 has been proven to be strong enough to prevent phagocytosis of antibody opsonized tumour cells when these cells express high quantities of CD47." (PMID 25158979, 2014). "We show that upon co-culturing APC with various primary and tumor cell lines STAT3 phosphorylation and IL-10 expression are induced, and such regulation could be suppressed by specific CD47 siRNAs and shRNAs." (PMID 24073274, 2013). "No detectable CD47 expression was observed in any tumor samples." (PMID 42278926, 2026). "High levels of CD47 protein expression have been widely reported across different tumor types and are an independent negative prognostic factor in multiple cancers, providing a strong rationale for disruption of the CD47/SIRPα axis as a therapeutic intervention." (PMID 41484790, 2026).